RNU1-22P (RNA, U1 small nuclear 22, pseudogene)
Gene: Small nuclear RNA gene on chromosome 16 (3,086,143 to 3,086,300, forward strand). Ensembl gene ENSG00000200204.
Homologues: Orthologues: chimpanzee U1 (90% identical), macaque U1 (76% identical), guinea pig U1 (68% identical), rat U1 (62% identical), rabbit U1 (55% identical), dog U1 (52% identical), mouse Gm23000 (51% identical), pig U1 (50% identical). Paralogues in human: RNVU1-28 (75% identical), RNU1-1 (74% identical), RNU1-2 (74% identical), RNU1-27P (74% identical), RNU1-28P (74% identical), RNU1-3 (74% identical), RNU1-4 (74% identical), RNVU1-18 (74% identical), RNVU1-29 (74% identical), U1 (74% identical), RNVU1-7 (73% identical), RNU1-89P (73% identical), and 134 more.